MIR192 (microRNA 192)
Synonyms: hsa-mir-192; MIRN192; miR-192; miRNA192
Gene: MicroRNA gene on chromosome 11 (64,891,137 to 64,891,246, reverse strand). Ensembl gene ENSG00000283926.
Gene Ontology:
Biological process: miRNA-mediated post-transcriptional gene silencing
Cellular component: RISC complex
Homologues: Orthologues: chimpanzee ptr-mir-192 (100% identical), macaque mml-mir-192 (90% identical), rat Mir192 (81% identical), guinea pig MIR192 (76% identical), mouse Mir192 (75% identical), pig ssc-mir-192 (72% identical), tropical clawed frog xtr-mir-192 (58% identical), dog MIR192 (57% identical).